PLEKHF1 (pleckstrin homology and FYVE domain containing 1)
Description:
May play a role in endosome function.
Synonyms: APPD; LAPF; ZFYVE15; MGC4090; PHAFIN1
Tractability: PROTAC: ubiquitination databases record sites on it; its protein half-life has been measured.
Gene: Protein-coding gene on chromosome 19 (29,665,398 to 29,675,477, forward strand). Ensembl gene ENSG00000166289.
Gene Ontology:
Molecular function: phosphatidylinositol-3-phosphate binding; phosphatidylinositol-4-phosphate binding; phosphatidylinositol-5-phosphate binding; protein binding; phosphatidylinositol binding; metal ion binding
Biological process: endosome organization; positive regulation of autophagy; protein localization to plasma membrane; vesicle organization; endosome to lysosome transport
Cellular component: endosome; lysosome; early endosome; endosome membrane; lysosomal membrane
Genetic constraint (gnomAD): Loss-of-function variants: 4 observed, 3.27 expected, observed/expected ratio (o/e) 1.22, 90% interval 0.56 to 1.9. That is too few expected variants to judge how well the gene tolerates losing a copy. Missense variants: 429 observed, 378.07 expected, observed/expected ratio (o/e) 1.13, 90% interval 1.05 to 1.23. Synonymous variants: 182 observed, 167.23 expected, observed/expected ratio (o/e) 1.09, 90% interval 0.96 to 1.23.
Homologues: Orthologues: chimpanzee PLEKHF1 (99% identical), macaque PLEKHF1 (99% identical), pig PLEKHF1 (91% identical), rat Plekhf1 (91% identical), dog PLEKHF1 (90% identical), mouse Plekhf1 (90% identical), guinea pig PLEKHF1 (89% identical), tropical clawed frog plekhf1 (63% identical), zebrafish plekhf1 (41% identical), Drosophila melanogaster CG6051 (19% identical), Caenorhabditis elegans lst-2 (16% identical), Drosophila melanogaster CG31064 (16% identical). Paralogues in human: PLEKHF2 (49% identical), ZFYVE26 (26% identical), ZFYVE16 (23% identical), ZFYVE28 (20% identical), RUFY1 (19% identical), RUFY2 (18% identical), ZFYVE1 (18% identical), PLEKHM2 (17% identical), RUFY3 (15% identical), SNX29 (13% identical), RUNDC3A (12% identical), ZFYVE19 (12% identical), and 1 more.
Diseases named in the same sentence as PLEKHF1 in open-access papers:
PLEKHF1 is named in the same sentence as 22 diseases in open-access papers, as found by Europe PMC text mining. Sharing a sentence is not in itself a finding about the gene and the disease. The quoted sentences say what the papers report.
breast carcinoma (3 papers, 2012 to 2021). "Silencing of CCNE1, PLEKHF1, POP4, ZNF536 and TSHZ3 expression selectively reduced cell viability in cancer cells harbouring 19q12 gene amplification but had a significantly lower impact on the survival of breast cancer cells lacking amplification of this locus (t-test P < 0.05)." (PMID 22433433, 2012).
breast tumors (1 paper, 2010). "In both ovarian tumor data sets analyzed the minimal mapped region of gain incorporated the same five genes (POP4, PLEKHF1, C19orf12, CCNE1 and C19orf2), with similar overlapping regions detected in endometrial and breast tumors." (PMID 21103391, 2010).
Hypertension (1 paper, 2025). The presence of chronic increased pressure in the systemic arterial system. "There were several genes affected by high-intensity interval training during HFD hypertension, which were Trim39, Nr4a1, Plekhf1, Tgm2, Lgals1, Egr1, and Atf3." (PMID 41516177, 2025).
osteosarcoma (1 paper, 2025). A usually aggressive malignant bone-forming mesenchymal neoplasm, predominantly affecting adolescents and young adults. "Gene expression comparisons between groups corroborated these findings, demonstrating significantly higher expressions of CERS1, FABP3 and NPDC1 in high‐mitophagy osteosarcoma, whereas PLEKHF1 and LILRA2 were significantly less expressed." (PMID 39834330, 2025).
ovarian carcinoma (1 paper, 2012). A malignant neoplasm originating from the surface ovarian epithelium. "Amplicon-dependent expression of CCNE1, together with the genes POP4, PLEKHF1, C19orf12 and C19orf2 that flank CCNE1 on this segment, was linked with primary treatment failure in ovarian cancer, possibly due to rapid repopulation of the tumor after chemotherapy." (PMID 22291905, 2012).
cancer (4 papers, 2012 to 2024). A tumor composed of atypical neoplastic, often pleomorphic cells that invade other tissues. "Expression levels of POP4, PLEKHF1 and CCNE1 were significantly higher in cancer cells harbouring amplification of the genes encoding these proteins than in cancer cells devoid of amplification of these loci (Mann-Whitney U test P < 0.05)." (PMID 22433433, 2012). "Further studies investigating the mechanisms that lead to a survival advantage in cancer cells harbouring amplification and overexpression of PLEKHF1 and POP4 are warranted." (PMID 22433433, 2012). "Silencing of POP4, PLEKHF1, CCNE1 and TSZH3 selectively reduced cell viability in cancer cells harbouring their amplification." (PMID 22433433, 2012). "As for BAG5 and PLEKHF1, they have not been investigated in OS up to now, while their role in some other cancers have been documented." (PMID 35504036, 2022). "Consistent with this hypothesis, we observed that cancer cells harbouring 19q12 amplification require the expression of not only CCNE1, but also PLEKHF1, POP4 and TSHZ3 for their survival." (PMID 22433433, 2012). "The 19q12 amplicon may harbour more than a single 'driver', given that expression of POP4, PLEKHF1, CCNE1 and TSZH3 is required for the survival of cancer cells displaying their amplification." (PMID 22433433, 2012). "Despite its reported role in apoptosis, PLEKHF1 siRNA-mediated silencing in cancer cells harbouring its amplification did not lead to an increase in the sub-G0 proportion of cells." (PMID 22433433, 2012).
tumor (4 papers, 2012 to 2018). "Changes in the expression of genes involved in apoptosis allow concluding about the activation of intrinsic mitochondrial pathway in tumor tissue after exposure to RNase A. We detected an upregulation of the genes Pycard, Plekhf1, and Dapk1, which activate the mitochondrial apoptotic pathway." (PMID 29108266, 2017).
adenocarcinoma (1 paper, 2025). A common cancer characterized by the presence of malignant glandular cells. "Copy number variants (CNVs) tend to be more prevalent in HAC than in common adenocarcinomas, and CNVs in CCNE1, VSTM2B, PLEKHF1, and POP4 are only present in HAC samples." (PMID 40740864, 2025).
infection (1 paper, 2025). The state of being infected such as from the introduction of a foreign agent such as serum, vaccine, antigenic substance or organism. "Nevertheless, genes related to anti-infection processes such as autophagy regulation (Plekhf1) or neutrophil recruitment (Cxcl2) were also induced." (PMID 41284621, 2025).
PLEKHF1 also shares sentences with these, for which no sentence is quoted: chronic graft versus host disease (1 paper); coronary heart disease (1); dependence (1); idiopathic pulmonary fibrosis (1); lymph node metastasis (1); mood disorder (1); myocardial infarction (1); ovarian tumor (1); Parkinson disease (1); prostate carcinoma (1); pulmonary fibrosis (1); serous ovarian cancer (1); tuberculosis (1).